PCA3 (prostate cancer associated 3)
Diseases named in the same sentence as PCA3 in open-access papers (continued):
Sharing a sentence is not in itself a finding about the gene and the disease.
tumor (continued). "It was also suggested that PCA3 could target miR-218-5p, a miRNA that negatively regulates PCa cell invasion, proliferation, migration and tumor angiogenesis." (PMID 31762940, 2019). "The description of PCA3 roles in PCa tumor biology was pioneered and reported by our group." (PMID 31762940, 2019). "Even though the range of PCA3 expression is different in tumor tissue and urine samples, the PCA3 trend in urine sample is very similar to tissue PCA3 suggesting that results from this study may hold true when conducted in large number of urine sample." (PMID 28881605, 2017). "Finally, the relationship between PCA3 score and the aggressiveness of the tumor is also controversial." (PMID 27792187, 2016). "PRUNE2 and PCA3 elicited opposite effects on tumor growth in immunodeficient tumor-bearing mice." (PMID 26437436, 2015). "The PCA3 ncRNA is one of the most prostate-specific genes described to date, is highly overexpressed in PCa tumors, and has been extensively characterized as a tumor biomarker." (PMID 23130941, 2012). "Our results suggest that the nuclear and microsomal cell compartments of prostate-tumor epithelial cells are the major sites of PCA3 expression, where PCA3 may play its main roles in controlling PCa cell pro-survival features." (PMID 23130941, 2012). "Considering the heterogeneity of PCa tumors regarding gene expression profiling and tumor progression behavior, we then wanted to evaluate survival features after PCA3 knockdown even in cell lines that express low PCA3 levels, and that in principle are androgen-independent." (PMID 23130941, 2012). "Moreover, numerous studies have demonstrated the correlation of PCA3 levels with tumor volume, suggesting that PCA3 utilization could significantly reduce the number of unnecessary prostate biopsies." (PMID 38793175, 2024). "Finally, we assess whether tumor expression levels of PCA3 and/or PRUNE2 are prognostic of biochemical disease recurrence after surgery." (PMID 36645410, 2023). "However, the expression of PCA3 was significantly lower in patients who died of their tumor." (PMID 32365858, 2020). "Similarly, the PEG3AP1-3STA system could complement current PCA3 or PSA assays by detecting circulating tumor cells (CTCs) and providing a more comprehensive assessment of disease monitoring." (PMID 30626088, 2019). "As expected after the discovery of the first lncRNAs in cancer like H19, MALAT1, PCA3, the list of lncRNAs involved in tumor progression and metastasis is growing and their role as prognostic biomarkers and as prominent therapeutic targets in tumor patients is becoming increasingly more evident." (PMID 30018188, 2018). "In addition, TMPRSS2-ERG, but not PCA3, was associated with the Gleason score and the tumor clinical stage." (PMID 27792187, 2016). "The mRNA transcripts for the fusion gene TMPRSS2:ERG were detected in two out of the four patients who had a high Gleason score and PSA levels, and not in the two low-risk tumours (patient 3 and 4), whereas PCA-3 transcripts were detected in all of the patients after mild prostate massage." (PMID 19401683, 2009). "At present, Prostate Specific Antigen (PSA) is still the core tumor marker used for diagnosing PCa in clinical practice, combined with Prostatic Acid Phosphatase (PAP) and Prostate Cancer Antigen 3(PCA3) for joint evaluation." (PMID 41445793, 2025). "Unsupervised principal component analysis (PCA) performed solely on the 53 tumor samples with a metabolic-41 expression program enabled the stratification of metastatic outcomes in patients (PCA1 p-value = 0.048 and PCA3 p-value = 0.042)." (PMID 39595571, 2024). "The mechanistic dysregulation of PCA3 and PRUNE2 is observed across the spectrum of tumor grades and stages, suggesting that this is an early and stable molecular event in prostate cancer." (PMID 36645410, 2023).
tumor (continued). "We consistently observed increased expression of PCA3 and decreased expression of PRUNE2 in prostate cancer compared with the adjacent normal prostate across all tumor grades and stages." (PMID 36645410, 2023). "In 24 of these cases (22.4%), we extracted RNA from benign prostatic glandular tissue away from tumor (hereafter termed ‘normal prostate’: qRT-PCR was successful in all cases for PRUNE2 [n=24, 100%] and in most cases for PCA3 [n=21, 87.5%])." (PMID 36645410, 2023). "Current PCa markers such as PSA, PCA3, TMPRSS2-ERG, and PSMA are expressed in PCa cells, but some of them are differently expressed depending on the location even in the same tumor from the same patient, complicating the implementation of a general therapy." (PMID 36008950, 2022). "PCA3 is an antisense lncRNA transcribed from intron 6 of the PRUNE2 gene, which acts as a tumor suppressor in prostate cancer." (PMID 32928281, 2020). "Progensa prostate cancer antigen 3 (PCA3) is a prognostic marker that measures the ratio of PCA3 to PSA (KLK3) mRNA and was found to be significantly higher in patients with mpMRI-visible tumours." (PMID 33000006, 2020). "PCA3 can bind PRUNE2 pre-mRNA to form a PRUNE2/PCA3 dsRNA structure, which undergoes adenosine ADAR-dependent A-to-I RNA editing, leading to decreased expression of PRUNE2 and increased tumor cell proliferation." (PMID 32928281, 2020). "Tumor incidence and positive predictive values for patients with high PSA, high PCA3 score and positive multiparametric MRI were calculated." (PMID 27286106, 2016). "PCA3 (also known as DD3 or DD3PCA3) is located on chromosome 9 and is transcribed into a non-coding prostate-specific mRNA which is overexpressed in tumor cells, from 60 to 100 times, when compared to the normal prostate tissue." (PMID 25651917, 2015). "Some studies have shown that PCA3 also correlates with tumor volume and can predict non-significant tumors (TV < 0.5 mL), but its value in predicting tumor aggressiveness (Gleason score ≥ 7, ECE) remains limited and inconclusive." (PMID 41374944, 2025). "Given that MCL patients with abundant tumor-infiltrating CD8+ T-cells and low levels of FTX or PCA3 lncRNA can predict poorer overall survival, it may be possible to include WTS analysis during diagnosis to improve MCL prognostication." (PMID 36359790, 2022). "To determine whether the PCA3 and MALAT1 scores were correlated with the tumor grade of PCa, we evaluated the PCA3 and MALAT1 scores in the clinically significant PCa (GS ≥ 7) with those in nonaggressive disease (PCa with GS6 and benign disease)." (PMID 34439239, 2021). "qRT-PCR of the lysate of cells captured in the microchannels indicated the presence of cells expressing AR and/or KLK3 but not necessarily that of tumor-derived PCA3 and PSMA genes." (PMID 34771706, 2021). "First, the initial 21 DE-kupl contigs and PCA3 validated for expression by NanoString were submitted to LASSO to define the best mixed signature comprised of already known and yet unannotated lncRNA probes for discrimination of tumor from normal tissues." (PMID 31732695, 2019). "PCA3 and TMPRSS2-ERG are commonly overexpressed biomarkers in prostate cancer, but reports have emerged demonstrating altered expression also in areas outside the tumour foci in cancerous prostates." (PMID 26294063, 2015). "In recent studies, PCA3 specificity was found even higher than prostate biomarker PSA and PCA3 score can accurately predict tumor volume and pathological features, which may guide treatment." (PMID 26448935, 2015). "Although broadly characterized as a PCa specific biomarker, to our knowledge, data on the roles of PCA3 in PCa biology and tumor progression have not yet been provided." (PMID 23130941, 2012). "P08-029pre, which came from a small tumor volume of 0.6 cc, showed marginal increase (2- to 3-fold above background) for these genes except for AMACR: AGR2 = 0.16, AMACR = 0.32, CRISP3 = 0.78, ERG = 0.28, HPN = 0.12, PCA3 = 0.19." (PMID 23029164, 2012).
tumor (continued). "Currently, we are still unable to discriminate between clinically important and indolent prostate malignancies, e.g., a low PCA3 score does not exclude a clinically significant tumor." (PMID 24281166, 2010). "In addition, the PCA3 assay has also been shown to lack utility as a marker for monitoring tumor progression, as does not correlate clearly with progression parameters." (PMID 41374944, 2025). "We showed that ARHGAP21 silencing in LNCaP prostate cancer cells decreased PCA3 and androgen receptor (AR) transcriptional levels and increased prune homolog 2 (PRUNE2) coding gene expression, indicating effective involvement of ARHGAP21 in androgen-dependent tumor pathway." (PMID 38896642, 2024). "However, although a sensitivity of 97.47% in PCA3 and a specificity of 90.32% in S100A4 was reached, the detection signal level could be variable in some analyses owing to tumor heterogeneity." (PMID 36613987, 2022). "Notably, within these early-passage organoids we identified a population fitting our profiling of ERG+ tumor cells, expressing a high level of LE cell markers (KLK3, KLK2, and ACPP) and tumor markers (PCA3, TRPM8, and ERG), which we annotated as putative tumor cells." (PMID 35013146, 2022). "The analysis of a cohort of 195 men showed that the expression of PCA3 and ERG genes (including the fusion gene TMPRSS2:ERG) normalised to the level of SPDEF (SAM-pointed domain-containing Ets transcription factor) can be used to differentiate between GS ≤ 6 and GS ≥ 7 tumours." (PMID 34811504, 2022). "Interestingly, in multivariate logistic regression analyses, only TMPRSS2:ERG added significant predictive value to the ERSPC-RC to predict biopsy Gleason score (OR, 7.16; P < 0.001) and clinical tumor stage (OR, 2.60; P = 0.023), whereas PCA3 did not." (PMID 26339615, 2015). "However, other investigators have pointed out that PCA3 is also expressed in the cytoplasm of tumor cells and is not expressed in the stromal compartment." (PMID 23130941, 2012). "PCA3 is a non-coding RNA and the most specific clinically available prostate malignancy marker described so far: PCA3 RNA expression is restricted to prostate, i.e., it is not expressed in any other normal human tissue nor in any other tumor." (PMID 24281166, 2010). "However, it is important to emphasize that positive PCA3 detection is not an indication of faster tumor development or invasiveness." (PMID 18823560, 2008). "In the present work, higher NOS3 transcript levels in peripheral blood of positive PCA3 patients than in negative ones suggest that tumor may be in a medium-late (pT2) stage of the disease and corroborates with the molecular approach for disease staging." (PMID 18823560, 2008). "However, PCA3 levels do not correlate with tumour grade or aggressiveness." (PMID 28241429, 2017). "The diminished PCA3 expression in the cytoplasm of BPH cells might be due to the loss of these transcripts, and the weaker positive staining may be an indication of the early development of a microfocal tumor event without morphological alterations." (PMID 26174796, 2015). "Tumor incidence and negative predictive values in patients with high PSA level and low PCA3 scores and negative multiparametric MRI lesions were calculated as well (Figure-1)." (PMID 27286106, 2016). "Potentially the response to ADT could also be followed, assuming that regression of the tumour resulted in less/no expression of the biomarkers, but the loss of expression could also be because of the reduced expression of androgen-responsive genes, like TMPRSS2 and PCA3." (PMID 19401683, 2009). "The ERG− tumor cell clusters were characterized by the enrichment of at least one known PCa gene-set signature and higher expression of tumor markers such as SPON228 and PCA3 compared to non-tumor LE cells in our dataset." (PMID 35013146, 2022).
infection (2 papers, 2008 to 2023). The state of being infected such as from the introduction of a foreign agent such as serum, vaccine, antigenic substance or organism. "But two distinct clusters form with PCA1 and PCA3 by infection status at 1 HPI indicating that the unigene profiles differ by infection status only at 1 HPI." (PMID 37896885, 2023). "PCA3 decreased during infection, with no apparent differences between infection regimes or infection doses." (PMID 18575588, 2008).
PCA3 also shares sentences with these, for which no sentence is quoted: colorectal cancer (4 papers); glioma (4); colon carcinoma (2); liver cancer (2); adenocarcinoma (1); atypical carcinoid tumor (1); carcinoid tumor (1); cervical cancer (1); chronic prostatitis (1); coronary artery disease (1); gastric cancer (1); hepatocellular carcinoma (1); inflammation (1); large cell neuroendocrine carcinoma (1); lung carcinoma (1); metastasis (1); muscular dystrophy (1); myocardial infarction (1); prostatic intraepithelial neoplasia (1); small cell lung carcinoma (1); viral infection (1).